SKP1 (S-phase kinase associated protein 1)
Diseases named in the same sentence as SKP1 in open-access papers (continued):
Sharing a sentence is not in itself a finding about the gene and the disease.
neurodegenerative disease (3 papers, 2016 to 2024). A disorder of the central nervous system characterized by gradual and progressive loss of neural tissue and neurologic function. "One of the functions of the SCF complex is to eliminate misfolded proteins, and various components of the complex (SKP1, Cullin1, FBXL5, FBXO7, FBXL18, Parkin) have been associated with neurodegenerative diseases." (PMID 34709416, 2021).
cardiac disease (1 paper, 2024). "Regarding the miRNA–mRNA pairs, miR-125a-5p/NIPAL4, miR-135a-5p/ZNF385B, miR-140-3p/FKBP3, miR-140-3p/SKP1 and miR-140-3p/NDUFA4, very little or nothing is known about the function of these genes in cardiac disease." (PMID 39200271, 2024).
SKP1 also shares sentences with these, for which no sentence is quoted: pancreatic cancer (3 papers); glioma (2); Alzheimer disease (1); aspergillosis (1); Burkitt lymphoma (1); cervical cancer (1); cholangiocarcinoma (1); chronic lymphocytic leukemia (1); colitis (1); immune deficiencies (1); ischemia reperfusion injury (1); laryngeal carcinoma (1); liver cancer (1); lung adenocarcinoma (1); myeloid leukemia (1); neuroblastoma (1); neurological disorders (1); Parkinsonism (1); rectal cancer (1); Salmonella Infections (1).